MRPS2 (mitochondrial ribosomal protein S2)
Description:
Required for mitoribosome formation and stability, and mitochondrial translation.
Synonyms: MRP-S2; S2mt; CGI-91; uS2m; COXPD36
Tractability: Small molecule: a structure with a bound ligand is known. PROTAC: ubiquitination databases record sites on it; its protein half-life has been measured.
Target class: Other cytosolic protein
Gene: Protein-coding gene on chromosome 9 (135,499,984 to 135,504,673, forward strand). Ensembl gene ENSG00000122140.
Subcellular location: Mitochondrion
Subcellular location (Human Protein Atlas): Mitochondria
Pathways (Reactome):
Metabolism of proteins: Mitochondrial protein degradation; Mitochondrial ribosome-associated quality control; Mitochondrial translation elongation; Mitochondrial translation initiation; Mitochondrial translation termination
Gene Ontology:
Molecular function: structural constituent of ribosome
Biological process: mitochondrial ribosome assembly; mitochondrial translation; translation
Cellular component: mitochondrial small ribosomal subunit; mitochondrion; mitochondrial inner membrane; mitochondrial matrix; ribosome; small ribosomal subunit
Genetic constraint (gnomAD): Loss-of-function variants: 14 observed, 18.77 expected, observed/expected ratio (o/e) 0.75, 90% interval 0.49 to 1.17. The upper end of that interval is the gene's LOEUF score, 1.17, which puts it in group 5 of 6, group 1 being the genes least tolerant of losing a copy. Missense variants: 389 observed, 426.87 expected, observed/expected ratio (o/e) 0.91, 90% interval 0.84 to 0.99. Synonymous variants: 186 observed, 180.94 expected, observed/expected ratio (o/e) 1.03, 90% interval 0.91 to 1.16.
Gene-disease validity (ClinGen):
ClinGen rates the evidence that MRPS2 causes each of these diseases.
mitochondrial disease (autosomal recessive): Moderate.
Homologues: Orthologues: chimpanzee MRPS2 (98% identical), macaque MRPS2 (89% identical), pig MRPS2 (74% identical), dog MRPS2 (73% identical), guinea pig MRPS2 (72% identical), mouse Mrps2 (70% identical), rat Mrps2 (69% identical), tropical clawed frog mrps2 (59% identical), zebrafish mrps2 (54% identical), Drosophila melanogaster mRpS2 (46% identical), Caenorhabditis elegans mrps-2 (31% identical).
Diseases named in the same sentence as MRPS2 in open-access papers:
MRPS2 is named in the same sentence as 8 diseases in open-access papers, as found by Europe PMC text mining. Sharing a sentence is not in itself a finding about the gene and the disease. The quoted sentences say what the papers report.
developmental delay (2 papers, 2025). "Mutations affecting MRPS2 were observed to cause mitochondrial disorder, altered cellular metabolism, developmental delay, and multiple defects in the oxidative phosphorylation system in a study by Gardeitchik and colleagues." (PMID 40843251, 2025).
Hypoglycemia (2 papers, 2022 to 2025). A decreased concentration of glucose in the blood. "We report a case of a new MRPS2 gene mutation in a Chinese girl who presented with hypoglycemia and lactic acidosis." (PMID 34991560, 2022). "Mitochondrial ribosomal protein S2 (MRPS2) gene mutation, which is related to severe hypoglycemia and lactic acidosis, is rarely reported globally." (PMID 34991560, 2022). "In the present study, we report a case of recurrent hypoglycemia with lactic acidosis in a school-aged child caused by a new MRPS2 mutation, which has not been reported, to reveal a rare cause of hypoglycemia and lactic acidosis in MRPS2 mutation and learn the phenotype of the MRPS2 gene." (PMID 34991560, 2022).
COVID-19 (1 paper, 2022). A disease caused by infection with severe acute respiratory syndrome coronavirus 2. "On the other hand, higher methylation of PSMB9, MRPS2, MFHAS1, and MAT2B genes are known to be expressed in COVID-19 patients with high viral load or severe infection, which could translate to a lower expression of those genes." (PMID 36371196, 2022).
glioblastoma (1 paper, 2021). The most malignant astrocytic tumor (WHO grade IV). "Furthermore, some evidence suggests that several genes expressing MRPs including bS1m (MRPS28), uS2m (MRPS2), uL23m (MRPL23), uS12m (MRPS12), bL12m (MRPL12) and mS34 (MRPS34) may be potential biomarkers for the treatment of glioblastoma with Benzyl isothiocyanate (BITC)." (PMID 34071057, 2021).
mitochondrial disease (1 paper, 2022). "Mitochondrial disease-causing mutations were found in thirteen small ribosomal subunit mitoribosomal proteins (MRPS1, MRPS2, MRPS6, MRPS7, MRPS9, MRPS11, MRPS14, MRPS16; MRPS22, MRPS23, MRPS25, MRPS34, MRPS39) and four large ribosomal mitochondrial proteins (MRPL3, MRPL12, MRPL24, MRPL44)." (PMID 36140315, 2022).
MRPS2 also shares sentences with these, for which no sentence is quoted: lactic acidosis (2 papers); Ataxia (1); infection (1).